CD47 (CD47 molecule)
Diseases named in the same sentence as CD47 in open-access papers (continued):
Sharing a sentence is not in itself a finding about the gene and the disease.
cancer (continued). "A CD47 antibody‐conjugated liposome was developed, and cancer cell membrane vesicles (CMV) were adopted to reversibly block the CD47 antibody to relieve the on‐target effect, forming CMV‐anti‐CD47‐Lip." (PMID 36683161, 2023). "High expression of CD24, CD47, and CD155 was associated with short overall survival (OS) in cancers." (PMID 38016957, 2023). "Hybrid nanovesicles and photothermal therapy combination methods promote DC maturation and improve the phagocytic capacity of macrophages by blocking the CD47-SIRPα axis between cancer cells and macrophages." (PMID 38017494, 2023). "The CD47/signal regulatory protein α (SIRPα) axis, which functions as an inhibitory phagocytosis checkpoint, also serves as a key mediator in cancer immune evasion." (PMID 36787255, 2023). "Cancer cells can evade immune surveillance through binding of its transmembrane receptor CD47 to CD172a on myeloid cells." (PMID 37241964, 2023). "Blocking of CD47/ signal regulatory protein α (SIRPα) is a new emerging era in cancer immunotherapy." (PMID 36774400, 2023). "Nowadays, SIRPα/CD47 is inhibited in combination with other checkpoint immunotherapies to treat multiple types of cancer." (PMID 36829496, 2023). "Immunohistochemical staining showed that the expression of STC1, AKR1B1, and CD47 was increased along cancer invasion." (PMID 36816947, 2023). "While lower expression levels of CD47 are observed in normal tissues, almost all cancer cells, including PDAC, overexpress CD47, which is independently correlated with a worse clinical prognosis in a wide variety of malignant tumors." (PMID 37189735, 2023). "Blocking CD47 and its receptor signal regulatory protein-α (SIRPα) can enhance the phagocytosis of macrophages or neutrophils to destroy cancer cells." (PMID 37427373, 2023). "Preclinical work has demonstrated encouraging anti-cancer effects of CD47-targeted inhibition in hematological and solid tumor xenograft and syngeneic models." (PMID 37958404, 2023). "Principles and strategies employed in CD47-related cancer immunotherapy can be appropriately adapted and applied to other medical conditions." (PMID 38125492, 2023). "Increasing studies report that targeting signal regulatory protein alpha (SIRPα)/CD47 results in therapeutic success in cancer treatment." (PMID 36829496, 2023). "When CD47 binds to SIRPα, it acts as a signaling mechanism that inhibits myeloid phagocytosis of the “self”, consequently impeding the elimination of cancer cells by phagocytes." (PMID 37894750, 2023). "CD47 has emerged as an important macrophage immune checkpoint that is overexpressed by many cancer cells, enabling tumors to evade macrophage phagocytosis." (PMID 37666809, 2023). "Cluster of differentiation 47 (CD47), a ligand of SIRPα, is an immunoglobulin-like transmembrane protein that is elevated in many cancer cells, including colon cancer cells." (PMID 37781354, 2023). "When the cancer cells were treated with macrophage culture supernatant, CD47 expression in cancer cells was increased." (PMID 36768216, 2023). "The principles and strategies employed in CD47-related cancer immunotherapy can be adapted and applied to other diseases." (PMID 38125492, 2023). "CD47 has been extensively studied and is known to play a critical role in immune evasion by cancer cells." (PMID 38125492, 2023). "The results of these trials will provide valuable insights into the potential of CD47-targeted therapies for cancer treatment." (PMID 38188674, 2023). "MYC oncogene, which plays a critical role in CRC, is known to promote CD47 and PD-L1 expression on cancer cells through binding to their corresponding promoters." (PMID 37291116, 2023). "CD47 is expressed on many different types of cancer cells, making it a potentially broad target for cancer treatment." (PMID 38188674, 2023). "The SIRPα/CD47 homeostatic function also occurs in the context of cancer to escape the immune system." (PMID 36829496, 2023).
cancer (continued). "Knockdown of RAGA not only enhanced the expression of CD47, but also increased the ratio of PM/intracellular CD47 levels in cancer cells." (PMID 36823443, 2023). "The recognition of tumors presenting CD47 macrophages and dendritic cells is impaired, therefore, anti-CD47 immunotherapy is a potential therapeutic target of cancer treatment." (PMID 37781354, 2023). "The antiphagocytic molecule CD47 is overexpressed in a wide variety of cancer cells, and antibodies targeting CD47 for cancer therapies are currently under intensive investigation." (PMID 36650558, 2023). "LRT treatment in vitro has been demonstrated to inhibit calcium influx and subsequently induce ER stress, resulting in the calreticulin upregulation and CD47 protein down-regulation in cancer cells." (PMID 37951973, 2023). "The authors concluded that the dissociation of oxidized CD47-SIRPα helps enhance tumor immunogenicity and support anti-cancer immune response, supporting its role in CAP-mediated cancer immunotherapy." (PMID 37759771, 2023). "On the other hand, CD47 is usually expressed on senescent cells and is abundantly expressed on the surface of various malignant tumor cells." (PMID 37740183, 2023). "Over-activation of CD47 triggers cell death pathway in a wide array of cell types such as immune cells and cancer cells." (PMID 38125492, 2023). "Several strategies to inhibit the CD47–SIRPα checkpoint have been evaluated in clinical trials for cancer IO." (PMID 37958404, 2023). "In summary, CD47-targeted therapy has shown promise as a potential cancer treatment, but there are several limitations and challenges that need to be addressed." (PMID 38188674, 2023). "Disruption of RAGA blocks CD47 degradation, leading to CD47 accumulation, high plasma membrane/intracellular CD47 expression ratio and reduced phagocytic clearance of cancer cells." (PMID 36823443, 2023). "CD47 is widely and highly-expressed in cancer cells and is one of the inhibitory ligands of myeloid cells." (PMID 37427373, 2023). "Among the various inhibitory receptors, CD47 was recently reported to be highly expressed in various types of cancers, resulting in NK cell dysfunction." (PMID 38037074, 2023). "Cancer cells are prevented from being phagocytosed by upregulating antibodies to CD47 on their surface, which interacts with signal-regulated protein alpha (SIRP) on macrophages to deliver the “don’t eat me” signal." (PMID 37644041, 2023). "CD47-SIRPα serves as an innate immune checkpoint and bridges innate and adaptive immunity in cancer." (PMID 37380989, 2023). "CD47, a transmembrane protein expressed on the cancer cell surface, is a critical immune checkpoint via interacting with macrophage surface protein SIRPα to prevent phagocytosis." (PMID 36823443, 2023). "Previous studies have shown that CD47 expression is higher in GC than in other, adjacent cancers, and that high CD47 expression indicates a poor prognosis 11,12." (PMID 36860925, 2023). "The CD47 overexpressed in many solid and hematological malignancies and directly relates to poor prognosis and survival of cancer patients." (PMID 38017494, 2023). "It is worth noting that the stable ASCL1 protein activates CD47 transcription and enhances cancer cell characteristics." (PMID 37783914, 2023). "Whereas low CD47-expressing cancer cells allow phagocytosis, their reverse signaling interferes with this process by partially activating a pro-survival function, leading to incomplete digestion of the entrapped cells and THC formation." (PMID 37848444, 2023). "CD47 is recognized as a promising immune checkpoint for cancer immunotherapy inhibiting macrophage phagocytosis." (PMID 37241964, 2023). "Supporting the positive associations between CD47 expression and these oncogenes, recent reports identified mechanisms whereby EGFR and KRAS upregulate CD47 expression in cancer cells." (PMID 37958404, 2023).
cancer (continued). "Downregulating CD47 on cancer cells discloses calreticulin(CRT) to macrophages and recovers their phagocytic activity." (PMID 36632842, 2023). "In this review, we briefly summarize how tumors disrupt the cancer immunity cycle to facilitate immune evasion and their exploitation of immune checkpoints like the CD47–SIRPα axis." (PMID 37958404, 2023). "Xenograft mouse models have been used in studies to evaluate the anticancer effects of CD47 blockade, and the results have revealed a significant inhibitory effect on various cancers 27-29." (PMID 36860925, 2023). "In summary, CD47 expression on cancer cells and stromal cells can regulate immune cell infiltration into the TME by inhibiting the expression of adhesion molecules and promoting the accumulation of immunosuppressive cells such as MDSCs and Tregs." (PMID 38188674, 2023). "High expression of merTK and CD47, for example, in CSCs and cancer cells would continue to promote their preservation while evading immune cell-mediated destruction." (PMID 38035101, 2023). "Taken together, we propose a model whereby strong CD47-SIRPα signaling not only represses macrophage encroachments but also enhances the survival of a cancer cell under this phagocytic attack." (PMID 37848444, 2023). "To date, how cancer cell CD47 protein stability is maintained on the cell surface remains to be investigated." (PMID 36823443, 2023). "CD47-SIRPα checkpoint is a myeloid cell-derived immune checkpoint that also plays an important role in inducing immune evasion of cancer cells like other immune checkpoints." (PMID 36109471, 2023). "The most well characterized CD47 interaction partners include thrombospondin-1, integrins, and members of the signal-regulatory protein (SIRP) family, which signal through CD47 to promote various hallmarks of cancer." (PMID 37958404, 2023). "Agents blocking the CD47-SIRPα axis improve macrophage phagocytosis, enhance programmed cell death of cancer cells, and promote macrophage-mediated ADCP or ADCC effects." (PMID 38008741, 2023). "SIRPα is expressed on TAMs and activated by CD47, an anti-phagocytic “don't eat me” surface protein expressed on cancer cells, particularly cancer stem cells." (PMID 37705736, 2023). "The binding of CD47 on cancer cells to signal regulatory protein-a (SIRPa) on macrophages results in the escape of cancer cells from phagocytosis." (PMID 36761751, 2023). "Therapeutic targeting the SIRPα/CD47 signaling axis is considered a promising strategy for the treatment of advanced cancers." (PMID 38164132, 2023). "CD47 is overexpressed on the surface of cells of many cancer types; as such, blocking CD47 can treat the progression of these cancers." (PMID 36894874, 2023). "Blockade of CD47-SIRPα interaction in cancer induces the activity of the innate immune system and increases phagocytosis of CSCs by macrophages." (PMID 36810098, 2023). "On the contrary, multiple miRNA have been shown to negatively regulate CD47 expression in several cancer types by degrading CD47 transcripts or blocking protein translation." (PMID 37958404, 2023). "Nanobodies targeting colony-stimulating factors or CD47 can be suitable substitutes in macrophage-based cancer immunotherapy." (PMID 36761751, 2023). "This inhibition of phagocytosis was not achieved by inhibiting the proliferative activity of macrophages as well as cancer cells A549, or the innate immunity CD47/SIRPα axis." (PMID 37259426, 2023). "SIRPα is an inhibitory receptor that binds to CD47 on cancer cells and suppresses microglial and macrophage phagocytosis." (PMID 37483607, 2023). "We investigated hypersialylation and CD47 expression in cancer cells and their role in modulating neutrophil cytotoxicity." (PMID 37444515, 2023). "This review aims to provide a comprehensive overview of CD47’s role in the TME of cancer patients receiving immunotherapy." (PMID 38188674, 2023).
cancer (continued). "By binding to CD47 on cancer cells, magrolimab blocks the signal, effectively removing the protection against phagocytosis." (PMID 37510328, 2023). "Several clinical trials are currently evaluating the safety and efficacy of CD47-targeted CAR T-cell therapy in cancer patients, along with pre-clinical studies." (PMID 38188674, 2023). "Various types of cancer express high levels of CD47 to escape from the immune system, and it is a prominent target in cancer therapy." (PMID 37056934, 2023). "The intricate complex system of the differentiation 47 (CD47) and the signal-regulatory protein alpha (SIRPα) cluster is a crucial target for cancer immunotherapy." (PMID 37375166, 2023). "CD47 on the surface of cancer cells binds to SIRPα on macrophages to inhibit macrophage‐mediated phagocytosis." (PMID 37409429, 2023). "In general, SIRPα is considered as the most important ligand of CD47 and targeting CD47-SIRPα axis is regarded as a novel strategy in the treatment of cancer." (PMID 38125492, 2023). "CD47 is a surface molecule on cancer cells that functions as a “don’t eat me” signal for TAM by engaging signal-regulatory protein alpha (SIRPα), an inhibitory receptor on macrophages." (PMID 36961012, 2023). "The CD47-SIRPα signaling pathway is thought to be a key mechanism by which cancer cells evade innate immune surveillance." (PMID 37740183, 2023). "In this study, we generated a bispecific antibody 6MW3211, which blocks both PD-1/PD-L1 and CD47/SIRPα pathways to boost both innate and adaptive immunity for cancer patients." (PMID 36593962, 2023). "CD47 can inhibit the phagocytic activity of macrophages to cancer stem cells by interacting with signal regulatory protein α (SIRP-α) on phagocytic cells." (PMID 36910604, 2023). "They further found that the deletion of APMAP combined with tumor antigen targeted monoclonal antibodies and/or CD47 blocking antibodies, significantly increase phagocytosis in a wide range of cancer cell types." (PMID 37427373, 2023). "Despite the challenges, CD47-targeted therapies present opportunities for improving cancer treatment." (PMID 38188674, 2023). "Several preclinical studies have investigated the efficacy of chimeric antigen receptor (CAR) T-cells targeting CD47 in eliminating cancer cells." (PMID 38188674, 2023). "High levels of CD47 have indeed been observed in both lymphoid and myeloid neoplasms, in which this factor is both an adverse prognostic indicator and a valid anti-cancer target with several therapeutic antibodies currently being tested in clinical trials." (PMID 37153563, 2023). "The elevation of CD47 protein expression by cancer cells serves as a mechanism to sidestep immune-driven eradication." (PMID 37822610, 2023). "Meanwhile, anti-CD47 antibodies have been confirmed as an inhibitor to cancer cell proliferation through the EGFR/PI3K/AKT signaling pathway." (PMID 37171006, 2023). "Elevated levels of CD47 expression have been consistently observed across multiple cancer types, encompassing solid tumors and hematological malignancies." (PMID 38188674, 2023). "The C-terminal domain of TSP-1 binds the extracellular region of CD47 at picomolar concentrations to control motility, proliferation, and angiogenesis that influence the invasive and metastatic properties of cancer cells." (PMID 37958404, 2023). "Altogether, our data suggested that activation of the GPR84-Gi signaling axis in macrophages can synergize with CD47 blockade to drive the phagocytosis of cancer cells." (PMID 37709767, 2023). "The binding of CD47-SIRPα inhibits macrophage phagocytosis of CD47-expressing cells, generating a “don’t eat me” signal and facilitating immune evasion by cancer cells." (PMID 38188674, 2023). "CD47, which is expressed on numerous cancer cell types, presents an attractive target for CAR T-cell therapy." (PMID 38188674, 2023).
cancer (continued). "Additional trial data that becomes available will inform more effective strategies for using CD47 blockade in specific cancer types, and therapeutic combinations to maximize therapeutic benefit." (PMID 37958404, 2023). "In physiological conditions, the SIRPα/CD47 pathway is involved in immunotolerance; however, in malignancy, it helps the cancer cells to achieve immune evasion." (PMID 36829496, 2023). "While CD47-targeted therapy has shown promise as a potential cancer treatment, there are several limitations that need to be addressed." (PMID 38188674, 2023). "CD47 molecule-mediated cancer cell self-protection is another potential mechanism of immune escape from CSCs, and inhibition of CD47 molecules can induce macrophage-mediated phagocytosis." (PMID 37422448, 2023). "Among all phagocytosis checkpoints, CD47 is the most thoroughly studied and has emerged as a rising star among targets for cancer treatment." (PMID 36882399, 2023). "Studies have shown that IFN-γ-induced CD47 upregulation is a common phenomenon in human cancers, and the JAK1-STAT1 axis is the main pathway." (PMID 37334368, 2023). "Several studies have demonstrated the enhanced therapeutic efficacy of dual blockade of CD47/SIRPα and PD-1/PD-L1 signaling in the treatment of different types of cancers." (PMID 36593962, 2023). "In this study, we demonstrate that CD47 localizes both on the cancer cell surface and in the cytoplasm, particularly colocalizes with endosomes and lysosomes." (PMID 36823443, 2023). "CD47 has emerged as a potential biomarker in cancer research, displaying distinct expression patterns in various malignancies." (PMID 38188674, 2023). "Integrin associated protein (IAP), or CD47, is another promising target overexpressed on cancer cells, including CSCs, in different types of hematological and solid tumors." (PMID 36900399, 2023). "CD47 is not only expressed on cancer cells but also stromal cells, including endothelial cells, fibroblasts, and immune cells within the TME." (PMID 38188674, 2023). "In various types of cancer cells and solid tumor tissues, high CD47 protein levels, which are mainly triggered by the transcription factor MYC, have been observed." (PMID 36966168, 2023). "How CD47 protein stability is maintained on cancer cell plasma membrane remains to be further answered." (PMID 36823443, 2023). "In the TME, overexpressed CD47 on cancer cells bind to SIRPα on myeloid cells, especially macrophages, monocytes, granulocytes, and CD4+ DCs, limiting phagocytosis and intracellular degradation." (PMID 38008741, 2023). "These dual effects highlight the potential of CD47 as a promising therapeutic target for cancer immunotherapy." (PMID 38188674, 2023). "Previous findings based on monoclonal antibodies (mAbs) or fusion proteins that block CD47 or SIRPα have been developed in cancer research." (PMID 37456027, 2023). "The finding that disruption of the SIRPα-CD47 interaction enhances phagocytosis of viable cells, contributed to the emergence of experimental targeting of CD47 for applications in cancer immunotherapy." (PMID 36813842, 2023). "For example, a translation blocking oligonucleotide to CD47 mRNA partially lowered total protein, and in combination with radiation, increased T-cell-mediated killing of cancer." (PMID 37217603, 2023). "In the following section, we describe CD47 and its expression, regulation, and functions in the context of cancer biology." (PMID 37958404, 2023). "Studies have extensively investigated the impact of CD47 expression on immunotherapy outcomes in cancer patients." (PMID 38188674, 2023). "Another major advantage of reprogramming TAMs to M1 for anti-cancer therapy is to exploit the phagocytic potential of M1 and consequently attack the CD47–SIRPα axis, already discussed in its involvement in immune evasion." (PMID 38035101, 2023). "By blocking CD47, the “don’t eat me” signal is disrupted, enabling phagocytic immune cells to recognize and eliminate cancer cells." (PMID 38188674, 2023).